KAT5 (lysine acetyltransferase 5)
Diseases named in the same sentence as KAT5 in open-access papers (continued):
Sharing a sentence is not in itself a finding about the gene and the disease.
prostate carcinoma (continued). "What’s more, KAT5 and KAT6B positively regulated prostate cancer cell proliferation through phosphatidylinositol 3-kinase (PI3K)/protein kinase B (Akt) signaling pathway, which was aberrantly activated in hepatocellular carcinoma." (PMID 35383533, 2022). "Collectively, these results suggested that KAT5-mediated circSMARCA5 biogenesis affects the circSMARCA5-miR-181b-5p-TIMP3 and/or circSMARCA5-miR-17-3p-TIMP3 axis in prostate cancer cells." (PMID 34390329, 2021). "In vitro KAT assays confirmed that salicylate directly inhibited PCAF/Kat2b, Tip60/Kat5 and hMOF/Kat8, and this inhibition was likely involved in the reversal of EMT in the metastatic prostate cancer cell line PC-3." (PMID 28717171, 2017). "Since the reduced growth of prostate cancer cells was not due to changes in the cell cycle, we examined apoptotic cell death in LNCaP cells following KAT5 overexpression." (PMID 31489246, 2019).
hepatocellular carcinoma (22 papers, 2011 to 2025). A malignant tumor that arises from hepatocytes. "KAT5/transformation/transcription domain-associated protein (TRRAP) exerted a role in promoting hepatocellular carcinoma cell proliferation by activating mitotic genes." (PMID 35383533, 2022). "In this study, both VPS72 and KAT5 were shown to be highly expressed in hepatocellular carcinoma cells, and their high expression was associated with poor prognosis." (PMID 35383533, 2022). "We found that KAT5 was O-GlcNAcylated by OGT in PCK1-deficient hepatoma cells, and O-GlcNAcylation of KAT5 enhanced its stability." (PMID 34650217, 2021). "Further studies are needed to verify whether TWIST1 can be acetylated by KAT5 in PCK1-deficient hepatoma cells." (PMID 34650217, 2021). "K (lysine) acetyltransferase 5 (KAT5) plays an indispensable role in the growth of hepatocellular carcinoma." (PMID 36986843, 2023). "The potential mechanism between VPS72 and KAT5 in the progression hepatocellular carcinoma was further investigated." (PMID 35383533, 2022). "KAT5 was highly expressed in the hepatocellular carcinoma cells lines Hep10, HuH-7 and SNU-387, and showed the highest expression in HuH7 cells." (PMID 35383533, 2022). "Collectively, VPS72 binding to KAT5 promotes the progression of hepatocellular carcinoma through the regulation of PI3K/AKT signaling pathway." (PMID 35383533, 2022). "Additionally, tail vein administration of exosomeRNP targeting KAT5 improved orthotopic hepatocellular carcinoma (HCC) transplanted via hepatic portal injection." (PMID 40006568, 2025). "Collectively, it is speculated that VPS72 may bind to KAT5 to promote proliferation, invasion and migration of hepatocellular carcinoma cells by regulating PI3K/AKT signaling pathway." (PMID 35383533, 2022). "Additionally, we only discussed the effects and regulatory mechanism of VPS72 and KAT5 in hepatocellular carcinoma cells." (PMID 35383533, 2022). "Subsequently, KAT5 was overexpressed to explore whether VPS72 could regulate the progression of hepatocellular carcinoma by binding to KAT5." (PMID 35383533, 2022). "All the information indicated that KAT5 may make an influence on hepatocellular carcinoma cells by PI3K/AKT signaling pathway." (PMID 35383533, 2022). "Recent studies have found that z-acetylation of KAT5 is associated with transcriptional misregulation of tumor signaling pathways in hepatocellular carcinoma, suggesting that KAT5 may be involved in the pathogenesis of hepatocellular carcinoma." (PMID 35602291, 2022). "Then, we investigated the O-GlcNAc modification of KAT5 in hepatoma cells." (PMID 34650217, 2021). "Then, we investigated whether loss of PCK1-mediated acceleration of the migration and invasion of hepatoma cells is dependent on KAT5." (PMID 34650217, 2021). "Furthermore, KAT5 can directly interact with the circRNA, circRHOT1, which is involved in hepatocellular carcinoma progression." (PMID 34390329, 2021). "Importantly, we found that O-GlcNAcylation increased KAT5 stability, thereby inducing epigenetic activation of TWIST1, associated with the acquisition of a metastatic phenotype in PCK1-deficient hepatoma cells." (PMID 34650217, 2021). "In our study, the data showed that the mRNA level of TWIST1 was upregulated in PCK1-deficient hepatoma cells, suggesting that PCK1 may transcriptionally inhibit TWIST1 by O-GlcNAcylation of KAT5." (PMID 34650217, 2021). "In lung cancer these include the lysine acetyltransferases KAT13D (Clock), KAT5 (Tip60), KAT2B (PCAF) and KAT13B (SRC-3), while SIRT-1 expression has been linked to cisplatin resistance in epidermoid and hepatoma cells." (PMID 24212667, 2011). "KAT5 belongs to the multiple KAT family members and is a potential therapeutic for several cancers, such as hepatocellular carcinoma and mesothelioma." (PMID 35383533, 2022).
hepatocellular carcinoma (continued). "Specifically, lysine acetyltransferase 5 (KAT5), belonging to the MYST family of histone acetyltransferases (HAT), is highly modified by O-GlcNAcylation in PCK1 knockout hepatoma cells." (PMID 34650217, 2021). "Importantly, we uncovered a novel mechanism that O-GlcNAcylation of KAT5, as a transcriptional regulator, epigenetically activates TWIST1 via enhancing histone H4 acetylation on the TWIST1 promoter, thereby inhibiting E-cadherin expression in PCK1-deficient hepatoma cells." (PMID 34650217, 2021). "Furthermore, exosome RNPs showed solid therapeutic potential in acute liver injury, chronic liver fibrosis, and hepatocellular carcinoma mouse models by targeting PUMA, CcnE1, and KAT5, respectively." (PMID 37166046, 2023). "In our study, upregulated KAT5 expression in HuH7 cells and the targeting binding of KAT5 and VPS72 identified by Co-IP detection revealed the fact that KAT5 may bind to VPS72 to affect the progression of hepatocellular carcinoma." (PMID 35383533, 2022).
colorectal cancer (14 papers, 2007 to 2025). A primary or metastatic malignant neoplasm that affects the colon or rectum. "In colorectal cancers, KAT5 down regulation is associated with more advanced stages of colorectal cancer." (PMID 23940558, 2013).
lung carcinoma (13 papers, 2009 to 2025). "A recent study has linked both KAT5 (Tip60) and HDAC6 as important regulators of lung cancer cell responses to cisplatin." (PMID 24212667, 2011).
melanoma (12 papers, 2014 to 2025). A malignant, usually aggressive tumor composed of atypical, neoplastic melanocytes. "Besides, metformin inhibits melanoma development by repressing KAT5-regulated SMAD3 acetylation." (PMID 35392432, 2022). "In terms of acetylation, metformin inhibits SMAD3 phosphorylation and hinders the KAT5-SMAD3 interaction, which reduces KAT5-mediated K333 acetylation of SMAD3 to inhibit SMAD3 transcription and TRIB3 expression, thereby restoring autophagy and combating melanoma progression." (PMID 37344841, 2023).
liver cancer (9 papers, 2019 to 2024). An epithelial or non-epithelial malignant neoplasm that arises from the liver. "The in vitro experiments demonstrated that overexpression of KAT5 and PD-L1 notably recovered abrine-caused suppression of liver cancer cell proliferation." (PMID 35602291, 2022). "For example, circRHOT1 induces liver cancer development by recruiting TIP60 (also known as histone acetyltransferase KAT5) to the promoter of nuclear receptor subfamily 2 group F member 6 (NR2F6), thereby inducing NR2F6 expression." (PMID 38697964, 2024). "In conclusion, our study reported that abrine inhibited PD-L1 expression in liver cancer cells via inhibiting epigenetic regulatory function of KAT5, which consequently promoted liver cancer cell proliferation and alleviated cell apoptosis." (PMID 35602291, 2022). "Further study with in vitro and in vivo model also manifested that KAT5 participated in abrine-suppressed liver cancer cell growth." (PMID 35602291, 2022). "Treatment with the conditioned medium from activated PBMCs stimulated PD-L1 expression of liver cancer cells, while KAT5 knockdown reversed this effect." (PMID 35602291, 2022). "Abrine modulated growth and apoptosis of liver cancer cells and regulated proliferation and activation of T cells through the KAT5/PD-L1 axis." (PMID 35602291, 2022). "We observed a decrease of KAT5 along with the PD-L1 in abrine-treated liver cancer cells; here, we wonder if KAT5 mediates the regulation of PD-L1." (PMID 35602291, 2022). "We discovered decreased level of KAT5 in liver cancer cells after abrine treatment." (PMID 35602291, 2022). "The proliferation and activity of T cells that cocultured with KAT5-overexpressed liver cancer cells were notably suppressed comparing with those cocultured with control cancer cells, whereas treatment with abrine significantly stimulated T cell proliferation and activity." (PMID 35602291, 2022). "We also determined the function of KAT5 in crosstalk between T cells and liver cancer cells." (PMID 35602291, 2022). "Within the multiple KAT family members, the importance of KAT5 is prominent, as silencing of KAT5 could be lethal Gorrini2007, and compiling evidences have revealed KAT5 as a potential therapeutic for several cancers, such as liver cancer and mesothelioma." (PMID 34406978, 2021). "To explore whether KAT5 mediates abrine-suppressed liver tumor growth through regulating T cells function, we evaluated proliferation and activation of T cells that cocultured with liver cancer cells under abrine treatment and KAT5 overexpression." (PMID 35602291, 2022).
myocardial infarction (7 papers, 2022 to 2025). Gross necrosis of the myocardium, as a result of interruption of the blood supply to the area, as in coronary thrombosis. "Using a murine model, we recently published findings demonstrating that CM-specific disruption of the Kat5 gene encoding Tip60 markedly protects against the damaging effects of myocardial infarction (MI)." (PMID 36341679, 2023). "In summary, we concluded that Res attenuated myocardial injury by inhibiting ferroptosis via inducing KAT5/GPX4 in myocardial infarction." (PMID 35685642, 2022). "Furthermore, polyphenol drugs that inhibit ferroptosis were found to alleviate myocardial injury through the KAT5/GPX4 pathway in myocardial infarction." (PMID 40124544, 2025). "Thus, we concluded that Res attenuated myocardial injury by inhibiting ferroptosis via inducing KAT5/GPX4 in myocardial infarction." (PMID 35685642, 2022). "In addition, resveratrol pretreatment can increase the expression of lysine acetyltransferase 5 and GPX4 in rat myocardial infarction model, suggesting that resveratrol can inhibit cardiomyocyte ferroptosis and alleviate cardiac dysfunction caused by myocardial infarction." (PMID 39744170, 2025).
viral infection (7 papers, 2017 to 2021). "In light of these findings, our current work adds HIV to the growing list of viral infections that employ KAT5 as a crucial regulator." (PMID 29684085, 2018).
leukemia (6 papers, 2014 to 2025). A malignant (clonal) hematologic disorder, involving hematopoietic stem cells and characterized by the presence of primitive or atypical myeloid or lymphoid cells in the bone marrow and the blood. "In T-ALL, Notch1 directly inhibited ATM kinase activity contributing to survival of Notch1-driven leukemias through impaired formation of FOXO3a-KAT5/Tip60 complex." (PMID 34680255, 2021). "Proscillaridin A induced a rapid loss of MYC protein expression in MYC-driven leukemia cells through the downregulation of series of KATs (KAT2A, KAT3A, KAT3B, KAT5 and KAT6A) known to be involved in MYC protein stability (by lysine acetylation) and activation of MYC transcriptional programs." (PMID 31196146, 2019).
diabetic nephropathy (5 papers, 2020 to 2025). "In our previous study in glomerular podocytes with diabetic nephropathy, KAT5-mediated DNA repair was associated with decreased DNA methylation." (PMID 34877495, 2021). "Although UV radiation caused a significant increase in KAT5 expression in cultured podocytes, high-glucose conditions caused decreased KAT5 expression in podocytes, which led to the accumulation of DNA DSBs in podocytes in diabetic nephropathy." (PMID 34630127, 2021). "Reduced KAT5 expression was observed in the glomeruli of diabetic nephropathy in mouse models and humans." (PMID 32099032, 2020). "In diabetic nephropathy, researchers found that GLIS family zinc finger 1 (Glis1) can bind and interact with lactoyltransferase KAT5, reducing the interaction of histone and KAT5, decreasing the lactylation level of histone, and alleviating the senescence of renal tubular epithelial cells." (PMID 40153584, 2025).
lymphoma (5 papers, 2006 to 2025). A malignant (clonal) proliferation of B- lymphocytes or T- lymphocytes which involves the lymph nodes, bone marrow and/or extranodal sites. "Mono-allelic loss of the human TIP60 gene (KAT5) is a frequent event in mammary and head-and-neck carcinomas and in human lymphoma." (PMID 31072879, 2019).
osteosarcoma (5 papers, 2019 to 2025). A usually aggressive malignant bone-forming mesenchymal neoplasm, predominantly affecting adolescents and young adults. "Wang and colleagues recently reported that Levobupivacaine epigenetically suppressed gene expression by downregulating KAT5, which enhanced cell apoptosis and reduced osteosarcoma cell invasion and migration." (PMID 41223512, 2025). "Regarding mechanism, we identified that levobupivacaine inhibited MAFB and KAT5 expression in osteosarcoma cells." (PMID 35333774, 2022). "Meanwhile, we provide a new function of KAT5 for the epigenetically inducing MAFB expression in the regulation of CSCs properties of osteosarcoma." (PMID 35333774, 2022). "In summary, we concluded that local anesthetic levobupivacaine inhibited stemness of osteosarcoma cells by epigenetically repressing MAFB though reducing KAT5 expression." (PMID 35333774, 2022). "Our mechanical study showed that levobupivacaine inhibited MAFB and KAT5 expression in osteosarcoma cells." (PMID 35333774, 2022). "Therefore, we concluded that local anesthetic levobupivacaine inhibited stemness of osteosarcoma cells by epigenetically repressing MAFB though reducing KAT5 expression." (PMID 35333774, 2022). "Moreover, it has been reported that KAT5 regulates the acetylation of KDM2B to enhance progression of osteosarcoma." (PMID 35333774, 2022). "The expression of MAFB was decreased by KAT5 knockdown in osteosarcoma cells." (PMID 35333774, 2022). "KAT5 contributes to the cell proliferation and stemness of osteosarcoma cells." (PMID 35333774, 2022). "KAT5 epigenetically enhanced MAFB expression in osteosarcoma cells." (PMID 35333774, 2022). "Meanwhile, KAT5 plays a crucial role in the modulation of osteosarcoma progression." (PMID 35333774, 2022). "The overexpression of KAT5 or MAFB could reverse levobupivacaine-attenuated cell proliferation and stemness of osteosarcoma cells." (PMID 35333774, 2022). "Moreover, we validated that the expression of MAFB and KAT5 was enhanced in clinical osteosarcoma tissues and the expression of MAFB was positively correlated with KAT5 in the tissues." (PMID 35333774, 2022).
glioma (4 papers, 2017 to 2025). A benign or malignant brain and spinal cord tumor that arises from glial cells (astrocytes, oligodendrocytes, ependymal cells). "We also examined whether genes upregulated after KAT5 loss (Neural G0 genes) differ significantly in expression in clinical glioma tumor surgical samples by IDH1/2 mutation status and/or grade." (PMID 40346033, 2025). "Finally, we wondered whether primary gliomas harbor populations with low KAT5 activity which would have molecular features associated with G0-like states." (PMID 40346033, 2025). "Further, increasing MYC expression in human neural stem cells stimulates KAT5 activity and protein translation, as well as confers sensitivity to homoharringtonine, to similar levels to those found in GSCs and high-grade gliomas." (PMID 40346033, 2025). "This dynamic interplay could be observed in primary gliomas, where tumors have dynamic KAT5 activity, which directly correlates with protein synthesis rates." (PMID 40346033, 2025). "However, KAT5 expression on its own failed to predict survival in IDH1/2 mutant or wt gliomas." (PMID 40346033, 2025).
ovarian carcinoma (4 papers, 2020 to 2023). A malignant neoplasm originating from the surface ovarian epithelium. "Bioinformatic analysis of the Australian Ovarian Cancer Study cohort (OV-AU) dataset suggests a higher incidence of NHEJ in ovarian tumors with low KAT5 expression, in both BRCA2-high and BRCA2-low backgrounds." (PMID 33257658, 2020). "We queried the OV-TCGA database and asked if ovarian cancer patients with low or high KAT5 expression showed any differences in survival, in BRCA2-mutant or BRCA2-wildtype backgrounds." (PMID 33257658, 2020). "Thus, we next sought to investigate if KAT5 expression impacts survival of BRCA2-mutant ovarian cancer patients by mining survival data and matched genotype and expression data from publicly available datasets." (PMID 33257658, 2020).
acute myeloid leukemia (3 papers, 2019 to 2025). Acute myeloid leukemia (AML) is a group of neoplasms arising from precursor cells committed to the myeloid cell-line differentiation. "Chromosomal translocations in some acute myeloid leukemia (AML) cases produce a fusion gene known as ZMYND11-MBTD1 (ZM), which recruits TIP60/KAT5 to stemness-related gene regions, including MYC, HoxA, Meis1, and Sox4." (PMID 41227365, 2025).
Anaplastic Thyroid Carcinoma (3 papers, 2022 to 2024). "The knockdown of K (lysine) acetyltransferase 5 (KAT5) has been identified to repress this enrichment, resulting in the autophagy and apoptosis of anaplastic thyroid carcinoma (ATC) cells." (PMID 38672404, 2024). "For examples, KAT5 could promote invasion and metastasis through C-MYC stabilization in anaplastic thyroid cancer." (PMID 35383533, 2022).
diabetes (3 papers, 2019 to 2023). "This study demonstrated that decreased urine KAT5/nephrin expression, which indicates primarily podocyte KAT5 expression, was observed in diabetes." (PMID 32099032, 2020). "In patients with hypertension and diabetes, DNA DSBs of the nephrin gene increased with decreased urine KAT5/nephrin expression, consistent with our previous study." (PMID 32099032, 2020). "This study has demonstrated that podocyte DNA DSBs increased with reduced expression of DSB repair factor KAT5 in patients with diabetes, using urine-derived cells." (PMID 32099032, 2020). "Urine KAT5/nephrin was decreased in patients with both hypertension and diabetes compared with controls or patients with hypertension alone." (PMID 32099032, 2020). "In addition, urine KAT5/nephrin significantly reduced in diabetes accompanied with hypertension compared to hypertension alone." (PMID 32099032, 2020).
malignant pleural mesothelioma (3 papers, 2019 to 2022). A malignant neoplasm that arises from mesothelial cells in the pleura and shows a diffuse growth pattern. "Whereas, the inhibition of KAT5 markedly suppressed the proliferation and induced apoptosis of malignant pleural mesothelioma cells." (PMID 35383533, 2022).
memory impairment (3 papers, 2019 to 2025). "Similarly, Tip60 (KAT5) reduction in the forebrain of adult mice causes substantial transcriptional impairments with concomitant neuronal cell loss in the hippocampal CA1 region that is accompanied by mild memory impairment." (PMID 40558500, 2025).
non-small cell lung carcinoma (3 papers, 2021 to 2022). A group of at least three distinct histological types of lung cancer, including non-small cell squamous cell carcinoma, adenocarcinoma, and large cell carcinoma. "Circular RNA circRHOT1enhances non-small cell lung cancer progression by epigenetically enhancing C-MYC expression through recruiting KAT5/H3K27ac axis." (PMID 35333774, 2022).
papillary thyroid cancer (3 papers, 2022 to 2023). "FosB recruits KAT5 to potentiate proliferation and metastasis of papillary thyroid cancer cells via modulating DPP4 function." (PMID 35392432, 2022).